IL6 (interleukin 6)
Diseases named in the same sentence as IL6 in open-access papers (continued):
Sharing a sentence is not in itself a finding about the gene and the disease.
uveitis (continued). "In the current era of pharmacotherapy for uveitis, we can theoretically target TNF, IL-1, IL-12/IL-23, IL-6, IL-17, CTLA4, CD20, etc.—various cytokines that have been identified in the serum and eyes of patients with different types of uveitis." (PMID 31523783, 2019). "In contrast, systemic treatment with Ac2-26 reduced the IL-1β, IL-6 and GRO/KC levels, confirming its anti-inflammatory role as having been demonstrated in other experimental models of neuroinflammation and uveitis and ocular allergies." (PMID 30755225, 2019). "Since the initial phase, the AnxA12–26 was able to reduce the expression of IL-1β, INF-γ, IL-6, TNF-α, and IL-17, corroborating studies with in vivo and in vitro models of retina autoimmune disease and uveitis in rodents and human." (PMID 30250432, 2018). "In an endotoxin-induced uveitis rodent model and in human ARPE-19 cells LPS-activated, an increasing of COX-2, IL-6, and IL-8 gene expression were found." (PMID 28420991, 2017). "Inflammatory cytokines, such as IL-6 and MCP-1, are induced in multiple retinal diseases other than uveitis, e.g., diabetic retinopathy." (PMID 26771918, 2016). "IL-6 and IFN-γ were detected in all aqueous humor samples from the patients with uveitis and the AR group, but the other cytokines were below the detection levels." (PMID 25303043, 2014). "The combination of the IL-10/IL-6 and IL-10/IFNγ ratios was highly informative for discriminating PIOL/OCL from uveitis samples and for therapeutic follow up of PIOL." (PMID 23405064, 2013). "Elevated levels of intraocular IL-6 and TNF-α, whose expression is upregulated by IRF5, have been reported in patients with intermediate uveitis, especially in those with macular edema." (PMID 24116155, 2013). "Because IFNγ and IL-6 seemed to increase the IL-10 level of discrimination, we calculated IL-10/IL-6 and IL-10/IFNγ ratios to improve discrimination of PIOL/OCL versus uveitis patients." (PMID 23405064, 2013). "The combination of the IL-10/IL-6 and IL-10/IFNγ ratios was highly informative in its discrimination between PIOL/OCL and uveitis samples." (PMID 23405064, 2013). "In the second part of this work, we analyzed the Th1/Th2 cytokine profile, including IL-10, IL-6 and IFNγ, in vitreous and aqueous humor samples from patients with PIOL, oculocerebral lymphoma (OCL), uveitis, and retinal detachment (as controls)." (PMID 23405064, 2013). "Despite the significant differences in the median IL-10/IL-6 and IL-10/IFNγ ratios between PIOL/OCL and uveitis samples, the range of values between these groups overlapped." (PMID 23405064, 2013). "The ocular fluids from BD patients with active uveitis contained significant amounts of inflammatory cytokines, such as IFN-γ, IL-2, TNF-α, IL-6, and IL-17." (PMID 22546542, 2012). "As shown in the current experiments, infliximab significantly suppressed IFN-γ, IL-6 and IL-17 inflammatory cytokines in addition to TNF-α produced by activated CD4+ T cells from BD patients who have active uveitis." (PMID 22546542, 2012). "Ocular fluids from active uveitis patients who have BD contained significant amounts of inflammatory cytokines such as IFN-γ, IL-2, TNF-α, IL-6, and IL-17, while ocular fluids from infliximab patients did not contain any inflammatory cytokines." (PMID 22546542, 2012). "We found significantly higher levels of IL-6 and IL-8 in patients with CME, which differs from the results from an earlier study on patients with uveitis of various origins." (PMID 21850175, 2011). "LPS-induced uveitis is often accompanied by elevated expression of cytokines such as tumor necrosis factor-α (TNF-α), interleukin-6 (IL-6), monocyte chemoattractant protein-1 (MCP-1)." (PMID 22040935, 2011). "Combined with our results, the data indicate that the major three factors (IL-6, IL-8 and MCP-1) are critical in multiple vitreoretinal disorders including uveitis." (PMID 19997642, 2009).
uveitis (continued). "Here, we show that the change of IL-10 mRNA expression and IL-6/IL-10 ratio during the first two weeks after CS therapy initiation can be used as biomarkers for refractoriness to CS treatment in uveitis patients independent of etiology of disease." (PMID 40433375, 2025). "The intense cytokine release (specifically IL-6 and IFN-γ) in CRS could disrupt the blood–ocular barriers, leading to inflammation (e.g. uveitis) or optic nerve edema." (PMID 41568391, 2025). "Elevated levels of IL-6 and TNF-α in uveitis patients may promote fibroblast activation and collagen deposition, leading to lacrimal duct fibrosis." (PMID 40687721, 2025). "Significantly increased levels of MCP-1, MIP-1β, IL-6, IL-8, TGF-β1, and TGF-β2 were found in the AH of USG patients, implying a potential role for these mediators in the progression of glaucomatous manifestations within patients with uveitis." (PMID 39407182, 2024). "The application of intravitreal anti-IL-6 treatment presents a promising therapeutic approach for addressing non-infectious uveitis." (PMID 39497001, 2024). "(Mean± standard deviation) IL-6 concentration in vitreous humor was 79.9±7380.9 pg/mL Uveitis was infectious in 9 cases and non-infectious in 28 cases with multiplex polymerase chain reaction system." (PMID 38232093, 2024). "Studies of serum cytokine levels in patients with noninfectious uveitis have consistently identified associations with elevated TNF-α, IL-6, IFN-γ and IL-17 A." (PMID 39075390, 2024). "Interleukin (IL)-6 is an inflammatory cytokine present in the eye during non-infectious uveitis, where it contributes to the progression of inflammation." (PMID 37097497, 2023). "The potential for classic signaling in human retinal endothelial cells has implications for the development of therapeutics targeted against IL-6-mediated pathology in non-infectious uveitis." (PMID 37097497, 2023). "IL-6 concentrations were compared between males and females for the infectious and non-infectious uveitis cases." (PMID 36902507, 2023). "We found that SKD MCs treatment also significantly reduced IL-6 expression in EAU, suggesting that it may suppress the production and progression of uveitis." (PMID 36313265, 2022). "The levels of EGF, fractalkine, IL1-β, IL-17A, IL-1RA, IL-2, IL-23, IL-8, IP-10, TNF-α and IL-6 in patients with uveitis in their active phase were independent of their counterpart levels in plasma, the difference being statistically significant (p < 0.05)." (PMID 36498608, 2022). "Previous studies have shown that expressions of IL-6, IL-8, and TNF-α were higher in uveitis." (PMID 36242032, 2022). "In proinflammatory cytokines, IL-6 increases approximately 13-fold in OT compared with control group, however, our study showed almost the same expression in OT and non-OT uveitis groups." (PMID 35646978, 2022). "In addition, previous researchers have found the increased expression of circulating CRP, IL-6, and TNF-α in the uveitis." (PMID 36275682, 2022). "In addition, some studies have shown that levels of inflammatory cytokines elevated in adults with RA, such as IL-6 and TNFα, are also elevated in the synovial fluid and serum of patients with JIA, as well as the aqueous humor of patients with JIA-uveitis." (PMID 34627340, 2021). "In this regard, significantly lower levels of TNF-α, IL-6, MIP-1α and leukocytes, as well as histological evaluation of TAC-HPβCD compared to EIU group confirms the effectiveness of this formulation in the treatment of uveitis." (PMID 34684030, 2021). "Although repeated injection of endotoxin resulted in the systemic release of IL-6, no IL-6 was detected in aqueous humor and no uveitis was found." (PMID 32671118, 2020). "Newer agents targeted against inflammatory factors such as IL-6 (e.g. IL-6 monoclonal antibody, tocilizumab) and janus kinase (JAK; e.g. JAK-inhibitor baricitinib) have also emerged as possible therapeutic agents for childhood uveitis." (PMID 33225212, 2020).
uveitis (continued). "Some uveitis patients had more IL-6 but the overall mean was not significantly different from the healthy donors." (PMID 31729418, 2019). "Furthermore, it has been reported that vitreous concentrations of IL-1, IL-6, and TNF-α were increased in an experimental uveitis rat model." (PMID 25679504, 2015). "Cytokines play a critical role in the pathogenesis of uveitis and we therefore investigated whether the different genotypes of rs2488457 affected production cytokines such as TNF-α, IL-1β, IL-6, IL-8, MCP-1, IFN-γ, IL-10 and IL-17." (PMID 24816862, 2014). "Indeed, 48% (11/23) of the uveitis samples had an IL-6 concentration in the same range as PIOL/OCL samples and 38% (10/26) of the PIOL/OCL samples an IL-10 concentration in the same range as uveitis samples, consistent with a previous report." (PMID 23405064, 2013). "Vitreous samples from 60 patients with PIOL (n = 17), OCL (n = 9), uveitis (n = 23) or retinal detachment (RD) without hemorrhage (n = 11) were analyzed for IL-2, IL-4, IL-6, IL-10, IFNγ, and TNFα concentrations by CBA." (PMID 23405064, 2013). "Finally, the graphic representation of the combination of the Logarithmic (Log10) conversion of IL-10/IL-6 and IL-10/IFNγ ratios helps to cluster the PIOL/OCL versus uveitis patients at diagnosis, with the upper right cluster specific for PIOL/OCL patients." (PMID 23405064, 2013). "Apparently, IL-6 and IL-8 are general markers of active uveitis and are not specific for particular uveitis entities." (PMID 21850175, 2011). "Thus, we propose that the systemic impact of intravitreally administered anti-IL-6 has no significant influence on uveitis in the fellow eye." (PMID 39497001, 2024). "A diverse array of cytokines, including IL-6, IL-4, IL-2, and IL-1, as well as intercellular adhesion molecule 1 (ICAM1), monocyte chemoattractant protein-1 (MCP-1), and tumor necrosis factor-α (TNF-α), are considered to be involved in the pathogenesis of uveitis." (PMID 39839649, 2024). "As an alternative therapy for the management of non-infectious uveitis, the use of Anti IL6 (tocilizumab or sarilumab), anti CD20 (rituximab) or Anti IL17 (secukinumab) has been tested in small case series, and a favorable response has been observed, although clinical trials are still pending." (PMID 37386509, 2023). "Thus, IL-6 is considered a general marker of active uveitis and is not specific for particular uveitis entities." (PMID 35646978, 2022). "Interleukin 6 is an important mediator of inflammation in uveitis and constitutes focus of research toward development of newer biological therapies in the management of non-infectious uveitis." (PMID 31523783, 2019). "It is also likely that the significantly higher levels of both IL-6 and IL − 8 among the HIV positive individuals could be attributed to a non-specific uveitis associated with HIV infection." (PMID 29351788, 2018). "Thus, increases of IL-6-induced STAT3 activation observed during inflammation may inhibit expansion of CD8-Tregs, thereby impeding recovery from uveitis." (PMID 24204098, 2013). "Studies have shown increased levels of IL-6 (T-cell cytokine) in the vitreous fluid of patients with active intermediate or posterior uveitis, although it did not correlate with a specific uveitis type, suggesting that IL-6 is an inflammatory mediator common in various uveitis etiologies." (PMID 23055575, 2012). "The treatment strategy for ICI uveitis could consist of topical corticosteroid injection (STTA or intravitreal injection), systemic corticosteroid administration, and/or discontinuation of ICIs or might include anti-IL-6 and tumor necrosis factor-alpha treatment." (PMID 40444081, 2025). "In addition to its anti-inflammatory effects, research has demonstrated that inhibition of IL-6 significantly improves uveitic macular edema, which has raised considerable interest among ophthalmic specialists regarding the therapeutic potential of TCZ in the treatment of uveitis." (PMID 39449328, 2024).
uveitis (continued). "As a novel target for autoimmune uveitis, IL-6 impacts the differentiation and stimulation of Th17 cells with TGF-β and IL-23, while considering that IL-1β is necessary for the production and regulation of IL-6, the inflammasome might be highly involved in the development of uveitis." (PMID 34925047, 2021). "In our current study, we performed ELISA to assess the protein levels of IL-10, IL-6, IL-17A, and TNF-α in the serum of non-infectious uveitis patients." (PMID 40433375, 2025). "In conclusion, the vitreous IL-6 level was significantly higher in male patients, and non-infectious uveitis cases showed a significant correlation between CRP and vitreous IL-6 levels." (PMID 36902507, 2023). "IL-6, TNFα, and CXCL10 were found to be significantly elevated in the aqueous humor (AH) of patients with BD uveitis, sarcoidosis, and toxoplasmosis uveitis as compared to non-inflammatory controls." (PMID 37297843, 2023). "Results revealed that levels of IL-6, IL-10, TNF-α, FLT3l, PDGF-AB/BB, and sCD40L were significantly increased in both OT and non-OT uveitis patients, compared with the control group levels." (PMID 35646978, 2022). "Comparison of classical monocytes between HC and uveitis patients revealed that common monocytic markers, e.g., CCR2, CX3CR1, HLA-DR, HLA-ABC, IL-6, IL-1β, and TNF-α were not affected (data not shown)." (PMID 30105034, 2018). "The IL-10/IL-6 ratio, as previously reported, was slightly higher in PIOL than in uveitis samples, but not for all patients." (PMID 23405064, 2013). "However, percent detectable of IL-10, IL-31, IFN-γ, sCD40L, and TNFα, and mean vitreous levels of IL-6, IL-10, IL-31, IFN-γ, sCD40L, and TNFα were significantly higher in eyes with uveitis than in those with ERM or MH (data not shown)." (PMID 26352837, 2015). "In conclusion, the combination of the IL-10/IL-6 and IL-10/IFNγ ratios could be very helpful as an initial screening to rule out PIOL in uveitis patients." (PMID 23405064, 2013).
Castleman disease (149 papers, 2008 to 2026). Castleman disease (CD) is a benign lymphoproliferative disorder that may present as a localized or multicentric form. "TAFRO syndrome is considered a clinical variant related to Castleman disease, which is also thought to result from dysregulated IL-6 signaling." (PMID 40351914, 2025). "Conversely, Castleman disease is associated with a more extensive cytokine imbalance, including elevated interleukin-6 (IL-6) and vascular endothelial growth factor (VEGF)." (PMID 39398672, 2024). "While IL-6 knockout mice have also been shown to present with heightened inflammatory responses with regional tissue damage, an excess of IL-6 is linked to Castleman’s disease, indicating the importance of the appropriate regulation of IL-6 levels." (PMID 33925531, 2021). "Castleman’s disease (CD) is a rare heterogeneous lymph node disorder associated with high levels of interleukin-6 (IL-6)." (PMID 30498913, 2019). "KSHV-associated multicentric Castleman’s disease has a waxing and waning presentation, closely associated with IL-6 levels." (PMID 30716130, 2019). "Castleman disease is caused by tumors overproducing IL-6, which in turn promotes an inflammatory state and excessive hepcidin expression." (PMID 27445804, 2016). "One person with associated Castleman’s disease received IL-6 inhibitor, Siltuximab." (PMID 40646134, 2025). "POEMS can also be associated with Castleman’s disease, an angiofollicular lymph node hyperplasia with several histologic subclasses but generally causing cytokine dysregulation with high IL-6 levels, lymphadenopathy, and B symptoms such as fever, night sweats, and weight loss." (PMID 38435320, 2024). "Castleman disease (CD) is an uncommon group of heterogeneous lymphoproliferative disorders that cause nonmalignant lymphadenopathy related to increased release of cytokines, particularly interleukin-6 (IL-6)." (PMID 37858241, 2023). "Notably, transfer of the vIL-6 gene into IL-6-deficient mice abolished these symptoms, suggesting that endogenous IL-6 is a causative factor for the development of multicentric Castleman’s disease." (PMID 34253862, 2021). "Castleman disease is a rare lymphoproliferative disorder characterized by generalized lymphadenopathy and multiple organ involvement that is linked to chronic overproduction of IL-6." (PMID 30469435, 2018). "Therefore, it seems possible that IL-6 produced by the neoplastic myxoma cells provokes the activation of monocytes–macrophages to secrete additional IL-6, causing mediastinal lymphadenopathy and multicentric Castleman’s disease in patients with cardiac myxoma." (PMID 38396907, 2024). "A pharmacological study suggested that, under TCZ, serum IL6 trough level rises in rheumatic arthritis patients (1.55-fold) and in Castleman disease (23-fold)." (PMID 40454296, 2025). "Among these, IL‐6 is particularly significant in the development and progression of Castleman disease." (PMID 41439207, 2025). "Castleman disease is a rare lymphoproliferative disorder induced by a cytokine storm primarily involving interleukin (IL)-6, a pro-inflammatory cytokine crucial for wound healing and infection response." (PMID 40098608, 2025). "Elevation of IL-6 levels after the initiation of tocilizumab in Castleman disease has been reported." (PMID 39958406, 2025). "Castleman disease is characterized by a cytokine storm, with IL-6 playing a central role in iMCD symptomatology, histopathology, and pathogenesis." (PMID 40098608, 2025). "An increase in interleukin (IL)-6 levels in patients with Castleman disease has been reported, and a correlation between IL-6 levels and clinical symptoms has also been reported." (PMID 39944226, 2025). "General checkup, the extremely elevated serum interleukin-6 and lymph node biopsy in the left submandibular region gave us an initial suspicion of Castleman’s disease." (PMID 38566262, 2024).